RGS2 (regulator of G protein signaling 2)
Diseases named in the same sentence as RGS2 in open-access papers (continued):
Sharing a sentence is not in itself a finding about the gene and the disease.
periodontitis (1 paper, 2022). An acute or chronic inflammatory process that affects the tissues that surround and support the teeth. "In this study, we assessed the expression of FOS, ITPR, RCAN1, and RGS2 genes in the circulation and affected tissues of patients with periodontitis compared with normal controls." (PMID 36090248, 2022). "Finally, the expression of RGS2 was lower in total periodontitis tissues compared with total control tissues, affected tissues obtained from men compared with male control tissue, and total blood samples of affected individuals compared with controls." (PMID 36090248, 2022). "Finally, the expression of RGS2 was lower in total periodontitis tissues compared with total control tissues (RME = 0.24, P-value = 0.01) and in total blood samples of affected individuals compared with controls (RME = 0.42, P-value = 0.05)." (PMID 36090248, 2022). "Future studies are needed to appraise whether the contribution of RGS2 in the pathogenesis of periodontitis is exerted through the modulation of bone structure." (PMID 36090248, 2022). "To test this hypothesis, we designed this study and measured the expression levels of FOS, ITPR, RCAN1, and RGS2 genes in the affected tissues and the circulation of patients with periodontitis vs. appropriate controls." (PMID 36090248, 2022).
peritonitis (1 paper, 2021). Inflammation of the peritoneum (tissue that lines the abdominal wall and covers most of the organs in the abdomen). "Mmp9, Rgs2 and Zfp36l2 were downregulated in both IL-1β-induced conditions, while Lyz2 and Lst1 were downregulated in IL-1β-induced pneumonitis but not peritonitis." (PMID 34001893, 2021).
Pulmonary hypoplasia (1 paper, 2023). "Gestational disorders during pregnancy in maternal body would give rise to neonatal healthy problems, such as pulmonary hypoplasia, and some previous reports have found that RGS2 is also involved in the growth and development of neonatal lung." (PMID 37649067, 2023).
serous ovarian cancer (1 paper, 2022). "Therefore, we retrospectively analyzed RGS2 and its association with the prognosis of high-grade serous ovarian cancer (HGSOC)." (PMID 36230542, 2022).
Urinary incontinence (1 paper, 2021). Loss of the ability to control the urinary bladder leading to involuntary urination. "Previous reported study synthesized the triazolone bearing compound Gαq-RGS2 signaling inhibitor and extensively evaluated the pharmacological activity against the urinary incontinence, which showed the beneficial activity in the urinary incontinence." (PMID 34311782, 2021).
cancer (42 papers, 2007 to 2025). A tumor composed of atypical neoplastic, often pleomorphic cells that invade other tissues. "Our findings demonstrate that the activation of S1P2 and S1P3 promotes cancer-associated cellular phenotypes, whereas RGS2 suppresses this activity through direct interactions with these receptors." (PMID 40754247, 2025). "S1P2 and S1P3 activation significantly enhanced cell migration and the expression of cancer-associated genes, effects that were effectively suppressed by RGS2 expression." (PMID 40754247, 2025). "A pan-cancer analysis also revealed a significant association of RGS2 with TMB, TIDE, and CD8+ T-cell infiltration in other cancer types as well." (PMID 36591293, 2022). "Low RGS2 expression is associated with an indolent cancer phenotype representative of a major fraction of primary PC." (PMID 30467386, 2018). "High RGS2 level at the time of diagnosis was associated with a shortened cancer specific survival (CSS)." (PMID 30467386, 2018). "On the other hand, high RGS2 correlates with a proliferative metastatic phenotype associated with progressed cancer." (PMID 30467386, 2018). "However, our findings indicate that RGS2 not only suppresses the expression of genes involved in cell migration but also reduces the expression of genes associated with cell growth, cancer cell invasion, and EMT." (PMID 40754247, 2025). "Aberrant RGS2 expression has been shown in several types of carcinomas and is associated with negative prognosis, suggesting that the regulation and function of RGS2 is reflective of the cancer cell type and tumor microenvironment." (PMID 35924235, 2022). "RGS2, in particular, is highly expressed in normal human cells but is significantly downregulated in cancer cells." (PMID 40754247, 2025). "Our findings show that RGS2 suppresses S1P2- and S1P3-mediated cancer-associated cellular phenotypes by interacting with these receptors and inhibiting Gα-mediated signaling." (PMID 40754247, 2025). "Cho’s study revealed that RGS2 enhances dormancy cancer cells’ anti-apoptotic ability induced by endoplasmic reticulum stress through modulation of ATF4 expression, correlating with tumor recurrence and chemotherapy resistance." (PMID 38918587, 2024). "RGS2 (Regulator of G Protein Signalling 2) is pivotal in driving cancer recurrence and drug resistance through mechanisms involving dormant cells." (PMID 39400959, 2024). "In our study, we demonstrate the activity and mechanism by which RGS2 expression in cancer cells regulates immune surveillance." (PMID 37014700, 2023). "CX3CR1low TEFF highly expressed regulators of G protein signaling (RGS1 and RGS2) that was related to lower infiltration to cancer." (PMID 37080999, 2023). "Pancancer analysis also showed that RGS2 was significantly associated with TMB, TID and CD8 + T-cell infiltration in other cancer types." (PMID 37924113, 2023). "These additional functions, which include angiogenesis, migration, and chronic inflammation, have led to the discovery of RGS2’s role in cancer pathology." (PMID 37014700, 2023). "Considering the potential clinical value of Exo-ceRNA networks in cancer, we constructed a novel survival-related ceRNA subnetwork (Exo has_circ_0050334-has_miR_182_5p-RGS2)." (PMID 35924235, 2022). "RGS2 is underexpressed in BC; its overexpression can inhibit epidermal growth factors or the serum-induced proliferation of cancer cells." (PMID 36299824, 2022). "So far, little is known about the RGS2-related protein interactions, the metabolomic effects of RGS2, and about its impact on cancer stem cell capacity in HGSOC." (PMID 36230542, 2022). "RGS2 is highly expressed in normal human cells but downregulated in cancer cells, including breast adenocarcinoma, wherein it plays a tumor suppressive function." (PMID 36299824, 2022). "Our qRT-PCR results confirmed that GPX3 and RGS2 were significantly downregulated in GC than in para-carcinoma tissues." (PMID 35721114, 2022).
cancer (continued). "Our results suggest that PAR4 activation contributes to cancer progression, which is attenuated in the presence of RGS2, RGS4, and RGS16." (PMID 32517689, 2020). "Numerous reports from different types of cancer linking increased RGS2 expression to diverse cancer phenotypes and patient outcomes suggest that tumour properties and origin are influential." (PMID 30467386, 2018). "In genes upregulated by BRG1 siRNA transduction, the regulator of G-protein signalling 2 (RGS2) gene is suggested to have an important role as tumour suppressor in several human cancers." (PMID 21102582, 2011). "It was increased still further in the F19-depleted cancers compared with all samples (including the 1089M cell line), some of which had levels of RGS2 expression 1,000-fold or more times that of the comparator." (PMID 18067675, 2007). "In addition to Gzmb and Ifng, the T6 cluster also exhibited a relatively high expression of Tnf, thereby corroborating the significant contributions of Rgs2+CD8+ T cells in the immune response against cancer." (PMID 40586324, 2025). "Studies have shown that the RGS2 gene also plays a certain role in cancer." (PMID 39132501, 2024). "Cancer cell dormancy and tumor relapse are mediated by RGS2-mediated translational control." (PMID 36199800, 2022). "Especially RGS2 has currently moved into focus of cancer therapy." (PMID 36230542, 2022). "A pan-cancer analysis has shown that RGS2 is expressed in many tumor types." (PMID 36591293, 2022). "Due to its distinct isoforms, RGS2 has various modes of (inter)actions in these cancers." (PMID 36230542, 2022). "Although not essential for its evaluation as a tissue biomarker, these aspects might dampen the role of RGS2 for specific cancer monitoring." (PMID 36230542, 2022). "Pre-existing data about the prognostic role of RGS2 in different cancers appear contradictory." (PMID 36230542, 2022). "Furthermore, PAR4 activation promoted cell proliferation and cancer-related gene expression, which were attenuated by RGS2, RGS4, and RGS16." (PMID 32517689, 2020). "In agreement with the patient data, we could show that cancer cells expressing low RGS2 levels displayed decreased metastatic properties compared to high expressing cells in terms of motility and colonializing ability." (PMID 30467386, 2018). "Aberrant RGS2 expression has also been reported for other carcinomas in association to both positive and negative prognosis." (PMID 30467386, 2018). "Aberrant RGS2 expression has also been described for other types of carcinomas in association to both positive and negative prognosis." (PMID 30467386, 2018). "Identification of the GPCR pathway(s) regulated by RGS2 in breast cancer will be key to assessing whether it has a critical function in cancer biology and whether this pathway is of value as a therapeutic target." (PMID 18067675, 2007). "One clue to the pathways involved may be that RGS2 was upregulated in the solid breast cancers, and in particular in the F19-depleted cancers, but tended to be less strongly expressed in cancer cell lines than in the normal tissue." (PMID 18067675, 2007). "Therefore, RGS2 is more characteristic of inhibiting cancer development than other members." (PMID 37924113, 2023). "Thus, translational suppression of PD-L1 expression by HITT/RGS2 may represent an alternative strategy against cancer and a marker for prediction of the anti–PD-1/PD-L1 response." (PMID 37014700, 2023). "It has also been reported that RGS2 expression could promote the migration and invasive ability of bladder uroepithelial carcinoma, and that inhibition of RGS2 expression in bladder uroepithelial carcinoma provides a promising target for the treatment of cancer." (PMID 37924113, 2023). "Also, the downregulation of RGS2 has been reported in the progression of various cancers." (PMID 36299824, 2022).
cancer (continued). "The markers GPX3, PDGFRL, RGS2, and SERPINE1 were found to be significantly increased in the high-risk group, suggesting that all of these markers may be implicated in the malignancy processes for STAD patients and may be cancer-promoting factors." (PMID 36199800, 2022). "Additionally, the data also show that although normal epithelia in the patient specimens expressed marginally more RGS2 than adjacent cancer cells, these regions displayed significantly less RGS2 staining than BPH specimens from cancer free patients (median score 2 and 8 respectively)." (PMID 30467386, 2018). "In this study, we demonstrated that RGS2 specifically interacts with S1P2 and S1P3 in live cells, leading to inhibition of receptor-mediated Gα signaling pathways, cell migration, and cancer-related gene expression." (PMID 40754247, 2025). "Our study demonstrates that activation of S1P2 and S1P3 significantly increases cell migration and cancer-related gene expression through ERK and AKT phosphorylation, and these effects were notably downregulated by RGS2." (PMID 40754247, 2025). "RGS2 is a protein that inhibits MAPK3 and AKT signaling in zebrafish and contributes to translational arrest in dormant cancer cells." (PMID 40305273, 2025). "The results revealed that RGS2 significantly suppressed agonist-induced expression of all tested genes, highlighting its inhibitory role in S1P2- and S1P3-mediated cancer-related gene expression in HCT116 cells." (PMID 40754247, 2025). "Upregulation was observed in many genes, including CAV2, FGFBP1, KRT19, MST1R, OCLN, and RGS2, which play important roles in the negative regulation of EMT and metastasis phenotypes in many cancers." (PMID 37298519, 2023). "Therefore, RGS2/HITT may contribute to PD-L1 regulation in vivo in human cancer tissues." (PMID 37014700, 2023). "There were widespread amplifications and deletions of five genes (GPX3, RGS2, MATN3, SLC7A2, and SNCG) across pan-cancer." (PMID 35721114, 2022). "RGS2 regulates G-protein signaling by accelerating hydrolysis of GTP and has been identified as a potentially druggable target in carcinomas." (PMID 36230542, 2022). "Previous studies reported that several RGS proteins, including RGS2, RGS4, and RGS5, were involved in cancer development." (PMID 28724429, 2017). "Furthermore, overexpression of RGS2 could suppress cancer cell growth." (PMID 25970626, 2015). "Regarding other putative targets, such as SEMA6D, RGS2 and ANGPTL1, their involvement and modulation in cancer has been demonstrated but their interaction with miR-182 have yet to be explored." (PMID 25115394, 2014). "Activity of p44/42 MAPK tends to be high in breast cancer, and so it is perhaps counterintuitive that RGS2, which suppresses p44/42 MAPK phosphorylation in oxytocin signalling, is highly expressed in breast cancers and cancer cell lines." (PMID 18067675, 2007). "Notably, RGS2 suppresses PAR4-mediated cell proliferation and the expression of cancer-related genes." (PMID 40754247, 2025). "Upregulation of several genes, including IGFBP4, RGS2, and WNT5A, that mediate several functions, including growth, differentiation, proliferation, apoptosis, and angiogenesis, were observed in cancer cells after their treatment with DBMSCs." (PMID 39768220, 2024). "In STAD patients, the genes GPX3, PDGFRL, RGS2, and SERPINE1 may be connected to the cancer process." (PMID 36199800, 2022). "Finally, PAR4-mediated HT29 cancer cell progression was significantly inhibited by RGS2, RGS4 and RGS16, as determined based on PAR4-activated cell proliferation and expression patterns of cancer progression-related genes." (PMID 32517689, 2020). "Additionally, both RGS2 and RGS4 attenuated PAR4-activated downstream signaling and cancer progression." (PMID 32517689, 2020). "Misexpression of RGS2, RGS4, and RGS5 has also been reported in a number of these cancers." (PMID 23637832, 2013).
cancer (continued). "In addition to cancer regions, sample 2 could also distinguish regions of breast ductal epithelial cells (cluster 6) with high expression levels of PTN, RGS2, CLU, and KRT15." (PMID 34799559, 2021). "Thus, targeting Rgs2 and MCP-1 signaling may have important clinical implications, and lead to a better prognosis for cancer patients." (PMID 21494556, 2011). "However, how RGS2 regulates T cell immunity and whether it has a role in the context of cancer immunity are not yet understood." (PMID 37014700, 2023). "The results showed that RGS2 and DUSP1 were significantly expressed in the cell population, and three model genes, CXCR4, SLCO2A1, and FNDC1, were not in the cluster, indicating that the two model genes that were significantly expressed could be used as marker genes of cancer." (PMID 36591293, 2022).
tumor (42 papers, 2007 to 2025). "For instance, RGS1 has been identified as a novel marker and promoter of CD8+ T cell exhaustion, while RGS2 is closely linked to the distribution and function of tumor‐infiltrating immune cells within the CRC tumor microenvironment." (PMID 40891683, 2025). "We found that the lower tumor mutation load in the group with high expression of RGS2 increased the difficulty of receiving the benefit of immune checkpoint inhibitors for patients." (PMID 36591293, 2022). "Some studies have indicated that RGS2 has a tumor suppressor function and that low expression of RGS2 is associated with a significantly poorer overall survival rate." (PMID 36615122, 2022). "This suggests a survival advantage of low RGS2 expressing tumour cells by the BCL-2 associated prevention of hypoxia-induced cell-death." (PMID 30467386, 2018). "Further analysis showed that tumour stroma expressed decreased levels of RGS2 compared to BPH associated stroma." (PMID 30467386, 2018). "In this study, we aimed to scrutinize aberrant RGS2 expression in terms of regulation and tumour advantage but also evaluate potential for diagnostic purposes and treatment." (PMID 30467386, 2018). "Rgs2 expression is elevated in tumor derived MDSCs, and hypoxia, a condition commonly associated with tumors, upregulates its expression." (PMID 21494556, 2011). "Yet, mechanisms for EMT might be enhanced on a protein level, since immunohistochemistry revealed a loss of RGS2 expression in tumor areas with solid growth in our own cohort." (PMID 36230542, 2022). "Interestingly, we identified an association between low RGS2 expression and sustained tumor cell plasticity on the single-cell level." (PMID 36230542, 2022). "Additionally, we suggest that the downregulation of RGS2 seen in early stages of PC is caused by moderate hypoxia and suggests that decreased RGS2 expression contribute to improved tumour cell survival and priming for later EMT." (PMID 30467386, 2018). "The description of HIF1A as an early marker for tumour development, lead to the assumption that hypoxia could cause decreased RGS2 expression in early PC." (PMID 30467386, 2018). "Additionally, improved tumour cell survival and increased BCL-2 expression linked decreased RGS2 levels to fundamental tumour advantages." (PMID 30467386, 2018). "Thus, this study identifies Rgs2 as a critical mediator of pro-angiogenic function associated with MDSCs in the tumor microenvironment." (PMID 21494556, 2011). "Of note, SYTOX Green Assay showed significantly more apoptosis of PDOs in Rgs2+CD8+ T cells cocultured groups, providing compelling evidence for the critical role of Rgs2+CD8+ T cells in anti‐tumor immunity." (PMID 40586324, 2025). "In both in vitro and in vivo MSS‐CRLM mouse models or PDO models, Rgs2+CD8+ T cells demonstrated significant tumor‐killing capabilities." (PMID 40586324, 2025). "In this study, we identified a notable enrichment of Rgs2+CD8+ T cells derived from T1_CD8_Ifit1_T cells in MSS‐CRLM tumor tissue following RegoNeo treatment compared to other treated groups." (PMID 40586324, 2025). "Mice injected with Rgs2+CD8+ T cells showed a significantly lower tumor burden than those in the control and Rgs2−CD8+ T cell groups, suggesting the crucial role of Rgs2+CD8+ T cells in antitumor immunity." (PMID 40586324, 2025). "Together, our data elucidate a distinctive mechanism by which PD-L1 expression is regulated and uncover antitumor activity of HITT and RGS2 through the prevention of tumor cell immune escape." (PMID 37014700, 2023). "Median RGS2 mRNA expression was 0 normalized mRNA reads per tumor cell (IQR 0.00–00) in all patients." (PMID 36230542, 2022). "Deletion of the RGS2 gene in mice significantly inhibited tumor growth and decreased tumor vascular density." (PMID 35879796, 2022). "When expressed, RGS2 was intensively and homogenously stained within tumor cells, particularly close to cell membranes." (PMID 36230542, 2022).